BDNF (brain derived neurotrophic factor)
Diseases named in the same sentence as BDNF in open-access papers (continued):
Sharing a sentence is not in itself a finding about the gene and the disease.
Obesity (continued). "Our work indicates that PVHBDNF neurons depend on RAI1 to maintain normal neuronal activity and regulate body weight homeostasis, and dysfunction of BDNF downstream signalling contributes to obesity associated with SMS mice." (PMID 37956053, 2023). "Considering ROC analysis results, the present study demonstrated that serum asprosin level compared to serum BDNF had an important predictive and diagnostic value in obesity." (PMID 37120612, 2023). "Considering these results, the present study demonstrated that serum asprosin level compared to serum BDNF had an important predictive and diagnostic value in obesity." (PMID 37120612, 2023). "Collectively, these findings suggest that QA-induced dopaminergic and glutamatergic neuron damage and BDNF downregulation are the cellular and molecular mechanisms underlying cognitive decline in obesity." (PMID 36787221, 2023). "In our cross-sectional study, we investigated the possible differences in obesity-related parameters dependently on daily energy and macronutrients intake in carriers of four BDNF genetic variants (rs6265, rs4923461, rs10501087, rs10835211)." (PMID 37085692, 2023). "Genetic variation of BDNF and the reduced protein expression of BDNF are associated to obesity in both human and animal models." (PMID 36334250, 2023). "Genetic variants that result in decreased production of BDNF have been shown to increase the obesity risk significantly in humans." (PMID 36839421, 2023). "Alterations in NGF and/or BDNF have been associated with several pathologic manifestations, including behavioral aberrations, cognitive deficiencies, tumorigenesis, obesity, and epilepsy, as well as muscle-skeletal, inflammatory, and pain sensitivity diseases." (PMID 36831321, 2023). "Their results show that mutations in the BDNF gene lead to leptin resistance, which is a major risk factor for obesity, despite the normal activation of leptin receptors." (PMID 36831706, 2023). "Studies in rodents and humans have shown that low levels of circulating BDNF are associated with metabolic dysfunctions such as obesity, metabolic syndrome and related disorders (e.g., diabetes, cardiovascular disease)." (PMID 38152248, 2023). "Given that mutations in Bdnf gene and BDNF haploinsufficiency result in obesity in both humans and rodents, the causal relationship between BDNF and energy homeostasis was widely accepted." (PMID 37238691, 2023). "Brain-derived neurotrophic factor (BDNF) is a risk gene of obesity, since some single nucleotide polypeptides (SNPs) of this gene are linked with obesity." (PMID 37238691, 2023). "Selective Rai1 loss from all BDNF-producing cells or from BDNF-producing neurons in the paraventricular nucleus of the hypothalamus (PVH) induced obesity in mice." (PMID 37956053, 2023). "Numerous in vivo studies have further proven the link between obesity and cognitive delay, involving the underlying biological mechanism related to insulin resistance, leptin, increased fat mobilization, brain-derived neurotrophic factor (BDNF), and cytokines." (PMID 37627544, 2023). "Mechanistically, it was proposed that various stimuli promote the release of BDNF from the endothelium, but several modifiable risk factors including obesity impair the magnitude of response resulting from shear stress." (PMID 36092801, 2022). "Humans with mutations in the BDNF gene or in the trkB receptor signal transduction pathway exhibit severe obesity." (PMID 35225959, 2022). "In experimental animals, BDNF protein deficiency due to variations in the BDNF gene, which causes obesity, is well established." (PMID 36676721, 2022). "The functional loss of one copy of the BDNF gene reduces serum BDNF concentration, increase ad libitum food intake and provokes severe early-onset obesity." (PMID 35242012, 2022). "Most likely, some BDNF genotypes resulting from BDNF gene polymorphism can be recognized as a potential factor in the development of obesity and insulin resistance." (PMID 35769087, 2022).
Obesity (continued). "Mutations in BDNF and its receptor, tropomyosin receptor kinase B (TrkB), are associated with hyperphagia and obesity in mice and humans." (PMID 35338053, 2022). "Reduction in brain-derived neurotrophic factor (BDNF) expression in the brain as well as mutations in BDNF gene or its receptor are associated with obesity in human and animal models." (PMID 35271679, 2022). "They provided evidence that rs10767664 and rs3751812 SNPs in the BDNF and fat mass are associated with obesity and obesity-associated (FTO) genes, respectively." (PMID 36676721, 2022). "Brain-derived neurotrophic factor (BDNF) and its receptor, tropomyosin receptor kinase B (TrkB), are implicit in causing obesity." (PMID 35338053, 2022). "The BDNF gene and protein have been linked to obesity in patients with various conditions, and a TrKB receptor mutation has been identified in obese children." (PMID 36676721, 2022). "The BDNF gene and protein have been linked to obesity in patients with various conditions, including Wilm’s tumor, aniridia, genitourinary abnormalities, and mental retardation contiguous gene syndrome." (PMID 36676721, 2022). "The diagnostic power of β-NGF and BDNF showed significant AUC values, and this helps for the early detection of obesity and associated risk factors in children." (PMID 35626286, 2022). "BDNF is a crucial component of the leptin-signaling cascade involved in energy homeostasis despite little being known about its association with obesity." (PMID 36676721, 2022). "Human studies have revealed association of the val66met BDNF polymorphism with obesity, suggesting a clinical role for BDNF signaling in feeding and body weight regulation, and this finding has recently been recapitulated in a mouse model." (PMID 36466807, 2022). "Reduction in BDNF expression in the brain as well as mutations in BDNF gene or its receptor are associated with obesity in human and animal models." (PMID 35271679, 2022). "Although the relationship between BDNF and obesity has yet to be defined, obesity is associated with increased risk of neurodegenerative disease." (PMID 36138878, 2022). "The loss of one copy of the BDNF gene in humans is also found to be linked with hyperphagia, severe obesity, reduced cognitive performance, and additionally, poorer locomotor activity." (PMID 36742047, 2022). "Many genes are associated with obesity, and the brain-derived neurotrophic factor (BDNF) gene is one of them." (PMID 36676721, 2022). "Central administration of BDNF can transiently suppress appetite, reverse abnormal eating behaviors and obesity, and lead to weight loss." (PMID 34482368, 2021). "We are the first to show that BDNF is differentially associated with brain responses to food cues in patients suffering from obesity and normal-weight participants." (PMID 33367955, 2021). "BDNF is an important pleiotropic protein directly related to neuron and brain health, commonly inversely associated with obesity." (PMID 34957187, 2021). "We examined this potential role, and found that 5-HT and BDNF mediated the association between overweight/obesity and EC." (PMID 33916706, 2021). "A study conducted among children in Beijing found that the association between BDNF rs6265 and obesity risk was only identified in children with moderate to low levels of PA or sedentary behavior." (PMID 33668547, 2021). "Strengths of our study included its novelty, and a high risk clinical sample of youth with obesity who exhibit greater incidence of BDNF-related complications such as neurocognitive deficits and metabolic dysregulation compared to peers without obesity." (PMID 34867148, 2021). "Previous genome-wide association study (GWAS) showed that the rs6265 polymorphism in the BDNF gene was closely related to obesity." (PMID 34482368, 2021).
Obesity (continued). "To further identify the pathways involved, we examined mRNA expression of relevant signaling molecules in the hypothalamus including brain-derived neurotrophic factor (BDNF) which is associated with obesity-induced hypertension and sympathetic activation." (PMID 34248679, 2021). "The brain-derived neurotrophic factor (BDNF) Val66Met polymorphism is functionally related to BDNF, and is associated with obesity and metabolic complications in adults, but limited research exists among adolescents." (PMID 34867148, 2021). "More recently, deletions in BDNF have been found in ~50% of patients with WAGR and the BDNF gene has been associated with obesity." (PMID 34970513, 2021). "This study aims to explore the unique genetic predisposition to obesity in former smokers by examining the effects of BDNF on BMI and waist circumference (WC)." (PMID 34525971, 2021). "BDNF is known to play a role in the control of energy balance and satiety, and further mutation in its gene can contribute to severe obesity." (PMID 33915758, 2021). "In conclusion, a PRS model using SEC16B_rs543874, DNAJC27_rs713586, BDNF_rs6265, MC4R_ rs6567160, and GIPR_rs1444988703 had gene−gene interactions which elevated the obesity risk." (PMID 34836030, 2021). "Hyperexpression of brain-derived neurotrophic factor in serum was associated with painful form of diabetic polyneuropathy (R=0.392, p=0.012) and obesity (R=0.412, p=0.001)." (PMID 34586159, 2021). "This study provides the evidence that 5-HT and BDNF mediated the association between overweight/obesity and executive control." (PMID 33916706, 2021). "The aim of this study is to investigate how BDNF, OSA and endothelial dysfunction interact in children with obesity and to determine the effect of weight loss on serum BDNF levels." (PMID 35127775, 2021). "7,8-DHF has been broadly validated in various BDNF-implicated disease models including a variety of neurological diseases, mental diseases, metabolic diseases, and obesity." (PMID 34227467, 2021). "The current study comparatively examined if adolescents with obesity carrying different variants of the BDNF Val66Met polymorphism differed on body composition, energy intake and cardiometabolic profile." (PMID 34867148, 2021). "Our study extends prior research by providing the evidence that BDNF and 5-HT are potential biological mechanism underlying the association between obesity and EC." (PMID 33916706, 2021). "Animal models have shown that BDNF deficient mice exhibit obesity and hyperactivity, symptoms that were reversible upon central BDNF infusion." (PMID 33572701, 2021). "In the case of rs925946 in the BDNF gene, the TG genotype (risk allele is T) showed significant association with obesity among psoriatic patients." (PMID 34685457, 2021). "The present study showed the participants with high PRS of appetite-related genes, mainly MC4R pathway-related genes, including SEC16B_ rs543874, BDNF_ rs6265 DNAJC27_ rs713586, MC4R_rs17782313, GIPR_ rs1444988703, increased the obesity risk by 1.6-fold." (PMID 34836030, 2021). "As well, we have previously reported that serum BDNF is negatively associated with diabetes risk factors in adolescents with obesity." (PMID 33013465, 2020). "The mRNA expression of BDNF has been identified in brain regions such as the hippocampus, cortex, and olfactory bulb, and dysregulated levels of BDNF have been associated with obesity." (PMID 33371327, 2020). "The results above suggested that the underlying obesity due to Western diet feeding for a prolonged time decreases neurotrophic mediator BDNF while increasing accumulation of phosphor Tau protein, a mediator for defects in memory and Alzheimer-like pathology." (PMID 32927823, 2020). "Based on previous significant findings, BDNF level is considerably linked to the alteration of metabolic risk factors leading to metabolic disorders such as obesity, diabetes, CVD, and CNS diseases." (PMID 33375318, 2020).
Obesity (continued). "Genome-wide association studies have identified many obesity/body mass index (BMI)-associated loci among which BDNF polymorphisms have been studied in different populations, not only on its association with obesity but the development of T2D." (PMID 33269104, 2020). "Obesity is associated with lower serum levels of BDNF in humans, while dietary restriction normalizes BDNF deficits in the brain in a mouse model of Huntington’s disease." (PMID 33297933, 2020). "Another point to be considered is the knowledge gap about the impacts that obesity and other chronic diseases (e.g., type 2 diabetes) can cause on BDNF levels and consequently on cognition." (PMID 32825341, 2020). "Two other molecular shreds of evidence with chromosomal inversion and child with perturbed TrkB receptor in hyperphagia supported by studies showing that BDNF haploinsufficiency is linked to hyperphagia and obesity." (PMID 32272767, 2020). "Mutations in BDNF and its receptor, TrkB, are associated with obesity and hyperphagia either in humans or mice." (PMID 32982666, 2020). "The underlying obesity in the GWI mouse model resulted in a significant decrease in BDNF and a parallel increase in phosphorylated tau protein, indicating a neurodegenerative phenotype associated with microbial dysbiosis." (PMID 32927823, 2020). "Further, BDNF has also been associated with eating disorders, glucose homeostasis, and some molecular determinants linked to food intake and obesity." (PMID 32272767, 2020). "As observed in POMC deficiency, genetic alterations in BDNF in humans is linked to elevated food intake and obesity." (PMID 32166324, 2020). "BDNF insufficiency or missense mutations in its receptor, TrkB, are associated with weight gain and obesity in humans and mouse models." (PMID 32942585, 2020). "Serum BDNF level was increased and associated with obesity in women with newly diagnosed type 2 diabetes mellitus." (PMID 33375318, 2020). "In conclusion, these data indicate the strong impact of lifestyle, in particular of the beneficial effect of PE, on the management of arterial thrombosis and inflammation associated with obesity in relation to the specific BDNF Val66Met mutation." (PMID 31405230, 2019). "In this study, exercise-induced reductions in some diabetes risk factors (most notably fasting glucose and beta cell insulin secretory capacity) were associated with increases in BDNF in adolescents with obesity." (PMID 31817641, 2019). "The Val66Met variant (rs6265) in the BDNF promoter region is the most investigated SNP of the gene, showing an association of cognitive impairment and obesity." (PMID 32116676, 2019). "Deletions encompassing BDNF have been causally implicated in the obesity and intellectual disability associated with the condition." (PMID 30242502, 2019). "This phenomenon has been explained by the fact that BDNF is also regulated by leptin, therefore leptin resistance—as one of the obesity-associated factors—shall be considered in future studies." (PMID 30767081, 2019). "Genome-wide association studies (GWAS) have shown a strong association between the BDNF locus and anorexia nervosa, bulimia nervosa, or obesity." (PMID 31405230, 2019). "It was shown that a low level of BDNF corresponds to numerous lifestyle-related diseases such as MetS and associated disorders like obesity, type 2 diabetes, heart failure, and acute coronary syndrome." (PMID 31341469, 2019). "Conversely, BDNF-deficient mice displayed hyperphagia, obesity, hyperleptinemia, and hyperinsulinemia." (PMID 31736870, 2019). "Our previous studies show that recombinant adeno‐associated virus (AAV)‐mediated hypothalamic BDNF gene transfer alleviates obesity, diabetes, and metabolic syndromes in both diet‐induced and genetic models." (PMID 30585393, 2019). "IF has been found to improve glucose tolerance and insulin resistance in heterozygous BDNF knockout mice and was associated with reduction of obesity and an increase in locomotor activity." (PMID 30479647, 2018).
Obesity (continued). "BDNF gene variants were studied as risk factors for metabolic complications, such as BMI, dyslipidaemia, obesity, insulin resistance and eating disorders." (PMID 30542302, 2018). "Reduction in brain-derived neurotrophic factor (BDNF) expression in the brain as well as mutations in BDNF gene and/or of its receptor are associated to obesity in both human and animal models." (PMID 30081509, 2018). "The VMH is considered as a satiety center and densely expresses brain derived neurotrophic factor (BDNF) and together with its receptor TrkB are genetically associated with human obesity." (PMID 29403354, 2018). "Increased BDNF levels were found in a population based study showing a positive association with increased risk for obesity, metabolic syndrome and coronary disease." (PMID 30542302, 2018). "This study examined the associations between changes in diabetes risk factors and changes in BDNF levels after 6 months of exercise training in adolescents with obesity." (PMID 30363954, 2018). "Low circulating BDNF is associated with both neurological and metabolic conditions including, major depressive disorder, Alzheimer's disease, obesity, and T2D." (PMID 30363954, 2018). "In order to disentangle these controversies regarding the association between circulating levels of BDNF and obesity, we performed a systematic review and meta-analysis of the literature." (PMID 30081509, 2018). "In conclusion, our data show that exercise-induced reductions in selected diabetes risk outcomes were associated with increases in resting serum BDNF levels in adolescents with obesity." (PMID 30363954, 2018). "This study investigated the independent associations between changes in serum BDNF, diabetes risk factors, and body composition following a 6-month exercise intervention in adolescents with obesity." (PMID 30363954, 2018). "Genetically, segmental deletions encompassing the WT1 and PAX6 genes are known to cause the syndromic phenotype, while an accompanying phenotype of obesity is linked to the extensive deletion involving the brain-derived neurotrophic factor (BDNF) locus." (PMID 29061165, 2017). "Deletion of BDNF is known eto be associated with hyperphagia and obesity in both humans and animal models; however, neuroendocrine and epigenetic profiles of individuals with WAGR syndrome remain to be determined." (PMID 29061165, 2017). "Both human and mouse data showed that decreased brain-derived neurotrophic factor (BDNF) is associated with the hyperphagia, development of obesity and neurodegenerative disease." (PMID 28209124, 2017). "The rs2049046 polymorphism is located at 5’ end of the BDNF gene, upstream to a region that contains obesity-associated SNPs." (PMID 28150221, 2017). "Among RAI1 target genes are Bdnf (brain-derived neurotrophic factor) and Htr2c (serotonin receptor 2c), both of which are implicated in hyperphagia leading to obesity, a phenotype accompanying SMS, concomitant with altered locomotor activity." (PMID 28548639, 2017). "As extraversion is known to be associated with lifestyle, obesity and substance abuse, we deem BDNF to be an interesting candidate gene for extraversion in future studies, along with CRTAC, ADAM12 and RELN." (PMID 26362575, 2016). "First, we did not assess other candidate genes which have been associated with obesity such as melanocortin-4 receptor (MC4R) gene as well as BDNF." (PMID 27196523, 2016). "Multivariate association between obesity on the BDNF AUC index at baseline cross-sectional assessment." (PMID 27787389, 2016). "BDNF is found in key brain regions involved in eating behavior, energy homeostasis, and weight control, and it has been linked to obesity and insulin resistance." (PMID 27685845, 2016). "In another case, a girl with loss of one functional copy of BDNF presented with hyperphagia, severe obesity, cognitive impairment and hyperactivity." (PMID 25825681, 2015).